HIF1A (hypoxia inducible factor 1 subunit alpha)
Diseases named in the same sentence as HIF1A in open-access papers (continued):
Sharing a sentence is not in itself a finding about the gene and the disease.
ischemic stroke (continued). "The results suggest that HBO may improve cerebral I/R injury, possibly via inhibiting HIF-1α, the upstream molecule of autophagy, and therefore, subsequently inhibiting autophagy in the rat model of ischemic stroke." (PMID 33816617, 2021). "In addition, the spatiotemporal expression profile of HIF-1α in the brain shifts with the progression of ischemic stroke; this has led to contradictory findings regarding its function in previous studies." (PMID 34966392, 2021). "In addition, Bu Yang Huan Wu decoction prevented ischemic stroke-induced reperfusion injury in rats by downregulating HIF-1α and VEGF and upregulating β-ENaC expression." (PMID 34434231, 2021). "After ischemic stroke, HIF-1a facilitates the processes of microglia chemotaxis, phagocytosis, and ROS and TNF-α production by promoting the expression of the phagocytic genes cd36 and mfg-e8, which have been shown to inhibit neurogenesis and lead to neuronal injury." (PMID 34966392, 2021). "As we found its expression rapidly rises in the penumbra after ischemic stroke, we wonder whether HIF-1α was also involved in the treatment effect of ADPN after ischemic stroke." (PMID 34336097, 2021). "However, few studies have focused on the role of HIF-1α in pericytes in the context of ischemic stroke." (PMID 34966392, 2021). "Further studies may focus on unveiling the biological function of HIF-1α in pericytes under pathological and physiological conditions, thus providing more favorable evidence on potential therapeutic targets for ischemic stroke." (PMID 34966392, 2021). "HIF-1α is now considered a potential novel therapeutic target for ischemic stroke." (PMID 34966392, 2021). "Such divergent effects of HIF-1α in ischemic stroke may be attributed to the diversity of downstream targets, which function in different cell types within the neurovascular unit (NVU)." (PMID 34966392, 2021). "In general, reversal of HIF-1α expression in the acute phase may be a worthy target for ischemic stroke therapy." (PMID 34966392, 2021). "In conclusion, our findings suggest that ADPN is effective in treatment of ischemic stroke which could be attributed to the increased antioxidant capacity regulated by HIF-1α." (PMID 34336097, 2021). "HIF-1α was also found to mediate the transcriptional regulation of chemokines monocyte chemoattractant proteins 1 and 5 in hypoxic astrocytes, which aggravates the neuroinflammation injury after ischemic stroke." (PMID 34966392, 2021). "Considering these characteristics, it is easy to hypothesize that there is a correlation between the therapeutic effects of HBO on ischemic stroke and HIF-1α." (PMID 33816617, 2021). "HIF-1α has been determined to play vital roles in certain ischemic diseases, such as ischemic stroke, liver, kidney ischemia/reperfusion injury, and retinal ischemic injury, but the exact mechanisms in acute glaucoma remain unclear." (PMID 32295623, 2020). "Indeed, it has been reported that HIF-1α contributes to the neuroprotective effect of NAC in an ischaemic stroke model of transient cerebral ischaemia in rats." (PMID 29670681, 2018). "It suggests that HDAC4 alteration may regulate the angiogenesis in ischemic stroke via HIF-1α-VEGF signaling." (PMID 30208931, 2018). "However, it has also been shown that HIF-1α improves neuronal survival during the early acute phase of ischemic stroke in the presence of ECs29." (PMID 29581463, 2018). "HIF-1α also showed neuroprotective effect in ischemic stroke." (PMID 28697748, 2017). "Activation of HIF-1α dependant signalling may therefore be potentially deleterious to neurons in ischaemic stroke." (PMID 28968430, 2017). "We therefore believe that HIF-1α in microglia may be a novel therapeutic target to promote neuronal survival in the hippocampus at the acute phase of ischemic stroke." (PMID 29340071, 2017).
ischemic stroke (continued). "Indeed, reduction of ROS by the liposoluble iron chelator 2,2′-dipyridyl in a rat photothrombotic ischemic stroke model was observed concomitantly with an increase in the level of HIF-1α protein." (PMID 28566998, 2017). "Therefore, we hypothesize that HIF-1α plays a protective role by regulating BNIP3-mediated mitophagy, and TENS might regulate mitophagy through HIF-1α/BNIP3 pathway in ischemic stroke." (PMID 37101593, 2023). "However, several studies have also pointed out that in the early stages of ischemic stroke, HIF-1α aggravates neurological damage by exacerbating the permeability of the blood-brain barrier and mediating the expression of proinflammatory factors and inflammatory responses." (PMID 36819784, 2023). "Based on our study, HIF-1α could be a potential therapeutic target for ischemic stroke." (PMID 34205911, 2021). "In addition, SIRT3 knockout mice reportedly show more severe BBB disruption and inflammatory responses than do wild type mice in the acute phase, suggesting an underlying regulatory mechanism of HIF-1α/VEGF signaling in astrocytes and harmful effects in the acute phase of ischemic stroke." (PMID 34966392, 2021). "However, the factors that induce the upregulation of HIF-1α in the acute phase of ischemic stroke remain unclear." (PMID 34434231, 2021). "Therefore, the role of baicalin on HIF-1α signal in ischemic stroke was still controversial, and experimental studies should be designed to evaluate the role of baicalin in acute phase and recovery phase of ischemic stroke." (PMID 30647760, 2018). "Therefore, the HIF-1α pathway could be a potential target for development of novel therapies for ischemic stroke." (PMID 28590414, 2017). "Also, HIF-1α modified or hypoxia conditioned mesenchymal or progenitor stem cells are an effective means of promoting their regenerative capability and therapeutic potential for the treatment of ischemic stroke." (PMID 28880966, 2017). "Hence, hypoxia inducible factor-1α (HIF-1α), an essential regulator of hypoxic events could be a useful target for the treatment of ischemic stroke." (PMID 26030758, 2015). "This review delineates the intricate mechanisms by which HIF-1α and the less-characterized HIF-3α modulate ferroptosis in ischemic stroke." (PMID 42254662, 2026). "As for ischemic stroke, SIRT3 exerted a protective effect by regulating the HIF-1α/VEGF pathway in astrocytes." (PMID 40969935, 2025). "Studies have documented that in murine models of ischemic stroke, inflammatory cytokines TNF-α and IL-1β, along with hypoxia-inducible factor 1-alpha (HIF-1α) activation, induce the expression of MMP-9 and MMP-2." (PMID 40746532, 2025). "HIF-1α induces NLRP3 inflammasome-dependent pyroptotic and apoptotic cell death following ischemic stroke in adult rats." (PMID 38674050, 2024). "For instance, Fluoxetine can upregulate protein expression in the HIF-1α-Netrin/VEGF cascade, promoting angiogenesis and improving long-term functional recovery after ischemic stroke." (PMID 38600597, 2024). "In conclusion, our results indicated that TENS alleviated brain damage following ischemic stroke via inhibiting neuronal oxidative stress and pyroptosis and activating mitophagy, possibly via the regulation of TXNIP, BRCC3/NLRP3, and HIF-1α/BNIP3 pathways." (PMID 37101593, 2023). "As shown in ischemic stroke rats, VEGF‐A, HIF‐1α, and VEGF‐R2 protein levels were increased at 14 days after MCAO compared to the sham group due to the endogenous protective effect of the body." (PMID 35855611, 2022). "Acidosis and free radicals have been shown to upregulate HIF-1α expression, and oxidative stress plays a critical role in BBB disruption during the reperfusion phase after ischemic stroke." (PMID 34434231, 2021). "In response to low tissue oxygenation during ischemic stroke, the activity of PHD and FIH declines resulting in stabilization of HIF-1α, its accumulation within the cell and translocation into the nucleus." (PMID 34439764, 2021).
ischemic stroke (continued). "Edaravone has been shown to prevent the HIF-1α from binding to the VEGF promoter in hypoxic astrocytes, thereby maintaining the permeability of capillaries and venules after ischemic stroke." (PMID 34966392, 2021). "Inhibition of HIF-1α by HIF-1α inhibitors such as 2-methoxyestradiol 35, mir-335 9 and hyperbaric oxygen 36 in the acute phase of ischemic stroke exerts beneficial effects via inhibition of apoptotic genes." (PMID 33162790, 2020). "Treatment with LSZ significantly alleviated BBB damage induced by ischemic stroke, which was accompanied by the downregulation of MMP-2/9, VEGF, and HIF-1α." (PMID 32215051, 2020). "HIF-1α and its downstream VEGF have been demonstrated to play significant parts in BBB integrity following ischemic stroke." (PMID 32215051, 2020). "Edn1 is regulated by Hif1-α and the lack of this anti-survival factor in Hif1-α deficient mice might protect from early acute neuronal cell death and neurological impairment in the very acute phase after ischemic stroke." (PMID 31660990, 2019). "Similarly, an adult rat ischemic stroke model demonstrated that acute alcohol exposure was neuroprotective in reducing infarct volume and improving motor skills due to acute alcohol-induced HIF-1α expression; this is likely due to its ability to increase angiogenesis." (PMID 30544759, 2018). "The research of Cheng focused on the expression and function of NICD and HIF-1α in ischemic stroke, while our focus was the benefit of up-regulation of NICD and HIF-1α expression induced by EA pretreatment in the focal cerebral ischemic injury." (PMID 25976178, 2015). "Inhibition of PHD activity resulted in HIF-1α stabilization, increased expression of VEGF and Epo, improved outcome from ischemic stroke and reduced edema formation by maintaining BBB integrity." (PMID 24409307, 2014). "Intriguingly, HIF-1α induces the expression of ACSL4, a ferroptosis mediator, in ischemic stroke." (PMID 40653468, 2025). "HIF-1α also regulates necroptosis-related proteins, such as RIPK3 and MLKL, in ischemic stroke." (PMID 38674050, 2024). "Furthermore, we aimed to explore the main regulatory mechanism of the HIF-1a/VEGF pathway on angiogenesis in NLXTD and provide a new idea for the treatment of ischemic stroke." (PMID 35449809, 2022). "ADRB2 is an important regulator of the neuroimmune response after ischemic stroke and affects the inflammatory response of microglia/macrophages, and inhibition of ADRB2-mediated upregulation of HIF-1α can reduce blood-brain barrier damage during acute cerebral ischemia." (PMID 34603472, 2021). "This suggests that at relatively later stages of ischemic stroke, HIF-1α is not a key player of brain injury, but of rehabilitative strategies." (PMID 33625674, 2021). "As we recently found out that HIF-1α was rapidly stimulated in the penumbra after ischemic stroke, we thought that HIF-1α might be involved in the treatment effect of ADPN after ischemic stroke." (PMID 34336097, 2021). "Notably, astrocytes mediate dual immunoregulation in ischemic stroke via the secretion of both proinflammatory and anti-inflammatory cytokines in response to changes in the cellular microenvironment, and the activation of HIF-1α may have a crucial role in regulating inflammatory responses." (PMID 34966392, 2021). "While further research is needed to uncover the significance of p38 MAPK and HIF-1α/VEGF signaling pathways in anti-inflammatory and neuroprotective effects, this study may represent a novel mechanism of LSZ in ischemic stroke." (PMID 32215051, 2020). "Globally, still significant high levels of HIF-1α with respect to the patients without history of ischemic stroke are evident through the study at the different time point considered." (PMID 30678250, 2019). "However, other studies have reported that inhibition of HIF-1α and HIF-2α is beneficial to the neurons in the very acute phase after ischemic stroke." (PMID 28979191, 2017).
ischemic stroke (continued). "Both, 2-methoxyestradiol (2-ME), a HIF-1α protein inhibitor and hyperbaric oxygen treatment could also inhibit HIF-1α in the acute phase of ischemic stroke to bring about the beneficial effects via inhibition of apoptotic genes." (PMID 26030758, 2015). "By synthesizing the distinct regulatory networks of HIF-1α and HIF-3α, this review underscores their potential as therapeutic targets and proposes that selective modulation of these pathways could offer novel neuroprotective strategies for ischemic stroke." (PMID 42254662, 2026). "Serum samples of 52 ischemic stroke patients showed a lower miR-210 expression level, with a variable mean of miR-210 between different time points (time of admission and 3 months after stroke) and a higher HIF-1α levels, which does not change in a time-dependent manner." (PMID 35757539, 2022). "Besides, it has also been reported that ischemic stroke increases HIF-1α expression levels, which could directly bind with NICD and NF-κB.197,198 Inhibition of both γ-secretase/Notch and HIF-1α significantly reduced cell apoptosis, while enhanced expression of NICD and HIF-1α increased NF-kB levels." (PMID 35794095, 2022). "But its neuroprotective role in regulating autophagy has not been investigated in the context of ischemic stroke, and it is unclear whether GP17 and active saponin of Panax Notoginseng stems regulate autophagy via Hif-1α/BNIP3 pathway." (PMID 36572901, 2022). "In addition, the overexpression of ChT1 in a HIF-1α-dependent manner is limited to young MCAO mice, and it may not completely recapitulate or summarize in patients with ischemic stroke in clinical trials." (PMID 34373737, 2021).
triple-negative breast carcinoma (92 papers, 2012 to 2026). An invasive breast carcinoma which is negative for expression of estrogen receptor (ER), progesterone receptor (PR), and human epidermal growth factor receptor 2 (HER2). "Simultaneously, the expression of the downstream gene of HIF1α was significantly upregulated in triple-negative breast cancer and was associated with prognosis." (PMID 36473847, 2022). "In triple-negative breast cancer, an increase in HIF-1α level is caused by excessive glutamate secretion." (PMID 36139678, 2022). "Recent studies demonstrated that hypoxia regulates specific variants (i.e. v6 and v7/8) of CD44 through HIF-1α in triple-negative breast cancer cells." (PMID 24586375, 2014). "It is worthwhile emphasizing that HIF1A also promotes the proliferation and invasion of triple-negative breast cancer (TNBC) by forming a complex with CARM1, which regulates the transcription of genes associated with hypoxic adaptation and tumor progression." (PMID 39995416, 2025). "MIR210HG specifically impacts triple-negative breast cancer (TNBC) by regulating HIF-1α at the translation level, thereby increasing HIF-1α protein expression and influencing the expression of glycolysis genes." (PMID 38799423, 2024). "Further studies have shown that hypoxic exposure of ER+ and triple negative breast cancer lines also increases the production of microvesicles (MVs), through HIF-1α induced expression of the RAB22A GTPase, which co-localises with budding vesicles." (PMID 39282472, 2024). "Correlative expression of LINC00115, methylation PLK3, SETDB1, and HIF1α are prognostic for clinical triple-negative breast cancers." (PMID 38520019, 2024). "Cardamonin inhibits glycolysis and the mTOR/p70S6K pathway by downregulating HIF-1α; this accelerates mitochondrial oxidative phosphorylation and ROS production, ultimately impeding the survival of the triple-negative breast cancer cell line MDA-MB-231." (PMID 37460927, 2023). "This study investigated the prognostic importance of HIF-1α and miR-210 in triple negative breast cancer (TNBC)." (PMID 36939902, 2023). "Previous evidence suggested that XBP1 promoted triple-negative breast cancer by controlling the HIF-1a pathway." (PMID 35915851, 2022). "The outcome of the HIF-1α downregulation in MDA-MB-231 was inconsistent with the results in another triple-negative breast cancer cell line, SUM149." (PMID 36139678, 2022). "Based on tissue sample studies, HIF-1α is expressed in most normal breast tissue, and its level is elevated in all triple-negative breast cancer samples." (PMID 36139678, 2022). "It has also been found that in human TNBC (triple-negative breast cancer) cell lines, the PD-L1 mRNA expression was increased due to augmentation of HIF-1α expression dependent on endoplasmic reticulum oxidoreductase 1-α (ERO1-α)." (PMID 36139678, 2022). "A recent study shows that LINK-A controls HIF-1α stabilization and activation of HIF-1α transcriptional programs under normoxic conditions in triple-negative breast cancer." (PMID 34877935, 2021). "In triple-negative breast cancer, XBP1 has been reported to be a pivotal role in the tumorigenicity and progression and XBP1 gene expression was highly associated with HIF1α and hypoxia-driven signatures." (PMID 34094948, 2021). "Recent studies found that XBP1 depletion from triple negative breast cancer cell models inhibited tumor growth and tumor relapse, and the active form of XBP1 was linked to the activation of HIF1α pathway and angiogenesis, and associated with poor prognosis." (PMID 32774853, 2020). "They reported that hypoxia promoted the triple negative breast cancer cell line MDA-MB-231 cell migration along with hypoxia-inducible factor 1-alpha (HIF-1α) accumulation and upregulation of chemokine (C-X-C motif) receptor 1 (CXCR1)." (PMID 30648081, 2018).